MTOR (mechanistic target of rapamycin kinase)
Diseases named in the same sentence as MTOR in open-access papers (continued):
Sharing a sentence is not in itself a finding about the gene and the disease.
breast cancer (continued). "FBXW7 LOF in several human cancers has multiple clinical implications, including prognostic value; for instance, rapamycin has been proven to inhibit FBXW7-deficient breast cancer cells by mTOR inhibition." (PMID 36901733, 2023). "Here, we report that DPP-4 deficiency promotes breast cancer cell survival via the induction of autophagy by the C-X-C motif chemokine 12 (CXCL12)/C-X-C receptor 4 (CXCR4)/mammalian target of rapamycin (mTOR)/hypoxia inducible factor (HIF)-1α axis." (PMID 37760498, 2023). "The secondary endpoints were to decipher the mutation types across breast cancer subtype, menopausal status, and time to treatment failure after everolimus (an mTOR inhibitor) or cyclin-dependent kinase 4/6 (CDK4/6) inhibitor treatment." (PMID 37655108, 2023). "The research discovered that mTOR signaling hyperactivation is linked to the development of breast cancer and resistance to targeted therapy." (PMID 38046946, 2023). "As a consequence, inhibitors targeting its constituents, like PI3K inhibitors (e.g., alpelisib) and mTOR inhibitors (e.g., everolimus), have emerged as particularly potent against certain breast cancer variants." (PMID 37762375, 2023). "Overexpression of mTOR is associated with poor prognosis of breast cancer, and phosphorylated mTOR is highly expressed in developed breast cancer." (PMID 37277807, 2023). "have analyzed 28,847 single nucleotide polymorphisms (SNPs) in 61 genes that participate in the mTOR pathway from 3,663 (1,983 ER+ and 1,098 ER-) breast cancer patients and 4,687 healthy women." (PMID 37251941, 2023). "In another study, the combined inhibition of BCL-XL and mTOR was found to synergistically induce apoptosis in PIK3CA-mutated breast cancer." (PMID 36588105, 2023). "The TSC/mTOR pathway is frequently deregulated in breast cancers and is associated with tumorigenesis." (PMID 37251941, 2023). "Mutation of the mTOR gene has been found only in some cancers, such as renal cancer, breast cancer, and ALL." (PMID 36980552, 2023). "Based on available knowledge, the PI3K/Akt/mTOR pathway is overactivated due to the PIK3CA mutations in up to 70% of brain metastases in patients with breast cancer." (PMID 37046703, 2023). "Overall, the PI3K/AKT/mTOR pathway is the most frequently mutated network in breast cancer and provides multiple molecular targets." (PMID 37345110, 2023). "MACF1 mutations were associated with upregulation of the mTOR signaling pathway and had a worse prognosis in breast cancer." (PMID 36779847, 2023). "Other common genetic alterations found in canine mammary cancer are mutations in the genes encoding proteins of the PI3K/Akt/mTOR pathway." (PMID 37835752, 2023). "Overactivation of the mTOR signaling pathway due to obesity, a result of positive energy balance, is associated with poor outcomes in patients with breast cancer." (PMID 36895729, 2023). "mTOR, a serine–threonine kinase, forms two complexes, mTORC1 and mTORC2, and is mutated in 1.8% of the primary breast cancer cases in The Cancer Genome Atlas, with a small minority of these mutations recognized as putative drivers." (PMID 36979714, 2023). "In human ER-positive MCF-7 breast cancer cells, lignans inhibited mTOR downstream effector molecules, causing autophagy-induced cell death with downregulation of ER." (PMID 37534085, 2023). "Since its discovery, the mTOR molecular pathway has been implicated in the pathogenesis of breast cancer and become a prominent therapeutic target in addition to targeting PIK3CA mutation." (PMID 37237509, 2023). "We further confirmed that the level of MTA1 was associated with the response of breast cancer patients to mTOR inhibitors." (PMID 37442756, 2023). "Taken together, these results indicate that metformin can attenuate DPP-4 deficiency-induced breast cancer autophagy and survival through suppression of the mTOR/HIF-1α pathway." (PMID 37760498, 2023).
breast cancer (continued). "Breast cancers frequently harbor mutations in the phosphoinositide 3-kinase (PI3K)/mechanistic target of Rapamycin (mTOR) pathway with activating mutations in PIK3CA or loss of function mutations in PTEN, together occurring in over 70% of cases." (PMID 37264081, 2023). "Body fat is positively correlated with the activation of the mTOR pathway, which is associated with tumor growth in breast cancer patients." (PMID 37700300, 2023). "The PI3K-protein kinase B (AKT)-mammalian target of rapamycin (mTOR) cascade is one of the major downstream signaling pathways in human cells, and its deregulation has been implicated in breast cancer development and progression." (PMID 36825198, 2023). "It appears that intracellular polyamines are linked to mTOR pathway regulation as transient knockdown of mTOR caused a decrease in polyamine content in the breast cancer cells." (PMID 36135836, 2022). "The results indicated that GDC-0084 is a potential compound in brain metastatic mammary neoplasms with a dysregulativity of PI3K/mTOR signals conferred by PIK3CA mutations." (PMID 36539659, 2022). "PTEN caused decreases in the levels of the FAK/PI3K/Akt/mTOR signaling pathway in association with EMT conversion in UA-treated breast cancer cells." (PMID 36613808, 2022). "ErbB receptor activity is associated with mTOR signaling, and mTOR inhibitors improve the outcome of ErbB2-positive breast cancer." (PMID 36120374, 2022). "In line with this, previous studies have also linked an increased PI3K/mTOR activity with dye exclusion abilities in breast cancer and glioblastoma." (PMID 36434616, 2022). "Previous studies shown that more than 70% of human colorectal and breast cancer is linked to gene mutations or gene amplification altered by the PI3K/Akt/mTOR pathway." (PMID 35250656, 2022). "Activation of mTOR signaling is a well-documented phenomenon associated with endocrine resistance and poor prognosis of ER+ breast cancer patients." (PMID 36304922, 2022). "Concurrently, MEK and PI3K/AKT/MTOR have been implicated as key primary resistance mechanisms in endocrine‐resistant ER+ breast cancers." (PMID 35671075, 2022). "Functionally, miR-216b was linked to breast cancer growth via inhibiting the mTOR signaling pathway by targeting HK2." (PMID 36428613, 2022). "The cell growth and tumor development in breast cancer are associated with the mTOR signaling pathway." (PMID 35795855, 2022). "This study uses both experimental and patient-based data to develop a biomarker for response to everolimus, and to understand the signaling underlying inhibition of mTOR signaling in ER+ breast cancer." (PMID 36304922, 2022). "Currently the stoichiometric mass action of this pathway remains to be investigated in these breast cancer subtypes, but several studies have linked methionine, mTOR, and insulin signaling pathways, albeit transitively." (PMID 35359364, 2022). "This is based on demonstrations that mutations in PI3K are more prevalent in TNBC than in other breast cancers, as well as on the activation of the mTOR pathway and its correlation with poor prognosis." (PMID 36060249, 2022). "Upregulation of cyclin D1 expression and RB phosphorylation and activation of the mTOR signaling pathway have been associated with resistance in ER + breast cancer." (PMID 36229710, 2022). "Increased stiffness, produced by high collagen density, is associated with higher YAP, cancer stem cell (CSC), and Akt/mTOR activity in mammary tumors in vivo." (PMID 35163745, 2022). "It is currently known that PI3K/mTOR proteins are highly expressed in human BC, which is associated with the development of breast cancer and osteolysis in vivo and in vitro." (PMID 35372035, 2022).
breast cancer (continued). "Using PCR-based techniques described in the Methods Section, we identified gene mutations related to the PI3K/Akt/mTOR pathway in 29.63% (16/54) of breast cancer patients." (PMID 33669698, 2021). "The mechanistic target of rapamycin (mTOR) pathway has been suggested as a mechanism underlying obesity and breast cancer development." (PMID 34330319, 2021). "The PI3K/Akt/mTOR pathway is frequently activated in breast cancer; of note, PIK3CA is the most common mutation in ER-positive breast cancer." (PMID 33462336, 2021). "Genomic analyses revealed that AA breast cancer patients show 28,847 single-nucleotide polymorphisms (SNPs) in intronic regions of 61 genes that were associated with the mTOR pathway." (PMID 33996789, 2021). "LAT1 inhibition has been associated with reduced cellular proliferation, often associated with reduced phosphorylation level of mTOR and its downstream effectors in several cancer models, including lung, colorectal and breast cancer." (PMID 33429909, 2021). "In the analyses stratified by tumor ER status, the difference in the association of BMI with breast cancer risk by p-mTOR expression status was significant among women with ER+ tumors (P-heterogeneity = 0.015), but not those with ER– tumors." (PMID 34330319, 2021). "The mechanistic target of rapamycin (mTOR) pathway promoted by positive energy imbalance and insulin-like growth factors can be a mechanism by which obesity influences breast cancer risk." (PMID 34330319, 2021). "The pathological activation of mTOR causes M2 over-polarization, which promotes metastasis in breast cancer cells." (PMID 35027915, 2021). "HER2-positive breast cancer is associated with hyperactivation of the mTOR pathway and a metabolic shift from aerobic respiration to glycolysis." (PMID 34208071, 2021). "AKT is central to the PI3K/AKT/phosphatase and tensin homolog (PTEN)/mTOR pathway, which is activated in almost 70% of breast cancers through mutations involving Akt1, PTEN, and PI3K." (PMID 34948307, 2021). "One often observed event in ER+/HER2− endocrine resistant breast cancers are mutations within the PI3K/Akt/mTOR axis, leading to a persistent activation of this HER2 down-stream pathway." (PMID 33920089, 2021). "For example, almost all of the published studies underline the role of mTOR hyperactivity in the progression and metastasis formation in hormone receptor–positive (HR +) or triple-negative (TN) breast cancers." (PMID 35029792, 2021). "Hyperactivation of this pathway is implicated in the development of breast cancer and frequently results in the upregulation of its main downstream effector, the mechanistic target of rapamycin (mTOR)." (PMID 33805424, 2021). "Loss of TSC2 expression and, therefore, abnormally enhanced mTOR activity, have been associated with lung‐metastatic potential in breast cancer." (PMID 34378323, 2021). "We evaluated the associations of body fatness with the risk of breast cancer varied with phosphorylated (p)-mTOR protein expression, an indication of the pathway activation." (PMID 34330319, 2021). "Our findings suggest that mTOR and its related signaling pathway is potentially an underlying mechanism by which body fatness influences breast cancer risk." (PMID 34330319, 2021). "Of note, recent work demonstrated that deregulation of protein translation associated with mTOR upregulation promotes breast cancer metastasis." (PMID 34052831, 2021). "In the subgroups, the association of BMI with p-mTOR overexpressed breast cancer appeared stronger in postmenopausal women (P-trend = 0.09) than premenopausal women (P-trend = 0.92)." (PMID 34330319, 2021). "In a panel of four mTOR pathway makers (mTOR, p-mTOR, p-AKT, and p-P70S6K) that we evaluated in patients with breast cancer, p-mTOR has the strongest association in relation to body fatness." (PMID 34330319, 2021).
breast cancer (continued). "Examination of canonical pathways associated with resistance to palbociclib in ER− breast cancer cells revealed a deregulation of PI3K/AKT/mTOR signaling." (PMID 33599863, 2021). "Gene mutations within the PI3K/Akt/mTOR pathway are identified in numerous types of malignancies, among others, lung cancer, brain cancer, colorectal cancer, ovarian cancer, breast cancer and uterus cancer." (PMID 33669698, 2021). "Overactivated mTOR signaling in breast cancer is linked to poor prognosis and decreased patient survival." (PMID 32012648, 2020). "The high frequency of mutations of PI3K/AKT/mTOR pathway found in breast cancer provides the rationale to test new inhibitors in combination with standard therapies." (PMID 32605126, 2020). "Using xenograft models of breast cancer, Formononetin showed growth-inhibitory activity associated with the inhibition of tumor angiogenesis and mTOR pathway." (PMID 32041350, 2020). "Studies have confirmed that mTOR inhibitor (everolimus) combined with trastuzumab reversed trastuzumab resistance via the hyperactivated PI3K-AKT-MTOR pathway due to PTEN deficiency in patients with HER2-positive advanced breast cancer." (PMID 32916316, 2020). "Hyperactive mechanistic Target of Rapamycin (mTOR) pathway is associated with breast tumor growth, but the extent to which body fatness is associated with mTOR pathway activities in breast cancer is unclear." (PMID 33024820, 2020). "One of the major oncogenic pathways in breast cancer is PI3K/AKT/mTOR, which is frequently upregulated by activating mutations in PIK3CA, MAP3K1, and AKT1, or inactivating mutations in PTEN, leading to increased growth signaling." (PMID 32926574, 2020). "Research and preclinical work conducted earlier have shown that stimulation of the mTOR signaling pathway is linked with resistance to hormonal therapy in ER+ breast cancer, and drugs that inhibit mTOR signaling can contribute in overcoming this resistance." (PMID 32489466, 2020). "Activation of PI3K/Akt/mTOR pathway has been associated with endocrine and cytotoxic therapy resistance in breast cancer with the majority of them occurring in hormone receptor (HR) positive tumors." (PMID 33299611, 2020). "Activation of the PI3K/Akt/mTOR pathway caused by aberrations at numerous points of genes contributes to the development of breast cancer." (PMID 32276228, 2020). "Activating mutations in genes related to the PI-3K/AKT/mTOR-pathway occur in 43-70% of breast cancer brain metastasis patients." (PMID 32194848, 2020). "Several studies have shown that mTOR activation (associated with high protein synthesis rates) can also promote the expression of breast cancer plasticity factors involved in EMT51." (PMID 32427827, 2020). "Previous studies in our laboratory have demonstrated that inhibitors of the PI3K/AKT/mTOR pathway have selective activity in ER+ breast cancer cell lines carrying activating mutations in PIK3CA." (PMID 32795346, 2020). "Supporting the findings of the CLEOPATRA study, we demonstrated that mutations in the PI3K/AKT/mTOR pathway are associated with poor overall survival following anti-HER2 therapies in patients with HER2+ breast cancer." (PMID 33303839, 2020). "Sal has been shown to induce iROS production, suppress the phosphoinositide 3-kinase/protein kinase B/mammalian target of rapamycin signaling pathways (PI3K/AKT/mTOR), and cause apoptosis in prostate, brain, and breast cancer cells." (PMID 32678032, 2020). "About 66.7% of patients with refractory breast cancer had at least one gene mutation in PI3K/AKT/mTOR pathway." (PMID 31385461, 2019). "The induction of mTOR activation was also associated with poor prognosis in solid tumor patients, such as breast cancer, melanoma, gastric cancer, and urothelial carcinoma." (PMID 31929797, 2019). "In breast cancer, most genetic alterations and mutations lie upstream of mTOR resulting in hyperactivation of mTOR signaling." (PMID 30754640, 2019).
breast cancer (continued). "The mTOR/STAT3 signaling pathway has been reported as a requirement for the growth of stem cell-like breast cancer SP cells, and it is implicated in the mediation of WA-induced apoptosis." (PMID 31319622, 2019). "DNA methylation at cg08862778 (MTOR gene) was statistically inversely associated with breast cancer (top tertile vs. bottom tertile, HR (95% CI) 0.57 (0.33, 0.97))." (PMID 30678711, 2019). "Various signaling pathways, such as the PI3K/Akt, STAT, intrinsic apoptosis, Hedgehog and Akt/mTOR signaling pathways, are linked to the pathogenesis of different breast cancer subsets and considered as potential targets for breast cancer therapy." (PMID 31409331, 2019). "It is reported that hyperactivation of the phosphatidylinositol 3-kinase/AKT/mammalian target of rapamycin (PI3K/AKT/mTOR) pathway is implicated in the tumor genesis of ER+ breast cancer and in resistance to endocrine therapy." (PMID 30713576, 2019). "In breast cancer, activated mTOR signaling is associated with poor patient survival and worse prognosis." (PMID 30148117, 2018). "In breast cancer cells resistant to AI, treatment with the mTOR inhibitor everolimus has been associated with dramatically reduced ER expression and increased autophagy in MCF-7 breast cancer cell lines." (PMID 30148117, 2018). "mTOR activation has been associated with resistance to SERMs and AIs and inhibition of the mTOR pathway is associated with resensitization of breast cancer cells to hormonal therapy." (PMID 30148117, 2018). "It has been reported that PI3K/AKT/mTOR pathway proteins are affected by specific mutations in breast cancer." (PMID 29614812, 2018). "Hyperactivation of the PI3K/AKT/mTOR pathway is frequently observed in breast cancer and is often associated with resistance to both anti-ERBB2-targeted and endocrine therapies." (PMID 29515110, 2018). "Dysregulation in the mTOR pathway have been implicated in the development of endocrine resistance in breast cancer, making this an attractive target for therapy." (PMID 29891002, 2018). "AKT1 activation has been linked to endocrine resistance, and treatment of early breast cancer with mTOR inhibitors reduces AKT signaling and proliferation." (PMID 29707142, 2018). "The effect of AM extract to suppress breast cancer cells growth was associated with its ability to inhibit PI3K/Akt/mTOR activity." (PMID 29523109, 2018). "In HER-2 positive breast cancer, our metabolomic approach confirms a fast and persistent host metabolism modification caused by mTOR inhibition." (PMID 29137365, 2017). "In short, the mechanism underlying the effect of the p-mTOR signaling pathway on breast cancer is complex, and numerous studies are necessary to elucidate it." (PMID 28114374, 2017). "PI3K/mTOR hyperactivation is linked to resistance to endocrine therapy of breast cancer in humans and dogs, resulting in tumor recurrence." (PMID 28451590, 2017). "In preclinical studies, PTEN deficiency or loss of PTEN is associated with responsiveness to mTOR inhibitors in endometrial cancer, Ewing sarcoma, and breast cancer." (PMID 29228674, 2017). "The combination of PIK3CA activating mutation and PTEN loss of function was associated with mTOR-pathway activation, most notably in the breast-cancer samples." (PMID 29137436, 2017). "Prospective studies are warranted to examine the association between p-mTOR expression and survival outcomes in breast carcinoma." (PMID 28114374, 2017). "Abnormal activation of the mTOR signaling pathway is associated with the development of many types of cancer and is present in 70% of breast carcinomas." (PMID 28114374, 2017).